IL5 (interleukin 5)
Diseases named in the same sentence as IL5 in open-access papers (continued):
Sharing a sentence is not in itself a finding about the gene and the disease.
eosinophilia (continued). "From a pragmatic, clinical perspective, phenotypic traits can be used in the daily clinical care to target-specific treatments: eosinophilia combined with exacerbations predicts effect of anti-IL5 and patients with fixed airflow obstruction and exacerbations may benefit from tiotropium." (PMID 29535852, 2018). "Specifically targeting DCs to modulate CD4+ T cell responses may represent a promising approach to treat allergic asthma where an enhanced Th2 response frequently leads to IgE production (IL-4), eosinophilia (IL-5), mast cell activation (IL-9), and AHR (IL-13)." (PMID 28439267, 2017). "Therefore, to investigate whether GR-MF are able to produce and secrete cytokines important in eosinophilia, we evaluated the expression of IL-5 and eotaxin, two relevant cytokines that control eosinophils." (PMID 26552582, 2015). "The role of eosinophils and IL-5 remains unclear, with some reports suggesting eosinophilia is critical for parasite clearance and others finding that IL-5 deficiency did not affect infectivity." (PMID 23518620, 2013). "Previous studies have also demonstrated that eosinophilia occurs between the 5th and 7th weeks after exposure to the parasite and may be induced by Th2 cytokines, such as IL-4, IL-10, IL-13, IL-9, and especially IL-5." (PMID 23401741, 2013). "Although infection of rodents with T. spiralis stimulated a basophilia as well as an eosinophilia, the parasite survival is not or marginally modified during a primary infection in IL-5-deficient mice, IL-5 transgenic mice, or in mice depleted of eosinophils with specific antibodies." (PMID 22360486, 2012). "The predominance of T helper-2 subset of T helper cells and the consequential increase in interleukin-5 cytokines accompanying peripheral eosinophilia and high serum immunoglobulin E levels may all be blamed for the development of eosinophilic panniculitis in our case study." (PMID 23148793, 2012). "Furthermore, blood eosinophilia and airway mucus production were also found to be normal in the Tim3-deficient mice, as were type-2 cytokine responses in the BAL fluid, as measured by IL-5 production." (PMID 21470319, 2011). "Thus, a basic level of IL-5 may be essential to drive eosinophils from bone marrow to blood and tissues, and for the maintenance of eosinophilia in infected animals." (PMID 18475693, 1996). "This was evidenced by elevated levels of IL-5, IL-13, and CCL11; enhanced eosinophilia; and higher numbers of total cells, lymphocytes, macrophages, and neutrophils in the BALF." (PMID 40587812, 2025). "Following challenge with np-Der p1 protein, immunized mice exhibited reduced allergic responses, including lessened eosinophilia, decreased Th2 (GATA3+ and IL-5+IL-13+) and Th17 (IL-17A+) cell frequencies, and lowered mucus production." (PMID 40985871, 2025). "The mice that received ST2+ cells had elevated lung eosinophilia compared to mice that received TCF1+ cells, fitting with the greater capacity of ST2+ cells to generate IL-5." (PMID 41256356, 2025). "Although HONK-treated mice (previously sensitized to and challenged with OVA) showed a significant decrease in lung eosinophilia, in our study, the combined administration of SECU and HONK induced an obvious IL-5 increase." (PMID 40872499, 2025). "Elevated levels of IL-5, either from intravenous cytokine injection, or in a genetic mouse model over-expressing IL-5 under the CD3 promoter, induce blood hyper-eosinophilia." (PMID 38585275, 2024). "BAL IL-5 levels have been reported to be higher in AEP than in chronic eosinophilic pneumonia, despite the lower level of eosinophilia." (PMID 38711783, 2024). "Inflammation with eosinophilia is regulated by the chemokines CCL11 and the cytokines IL-13, IL-5, and IL-33." (PMID 36970065, 2023). "This also reduced their expression of Gata3, Il4, Il5, and Il13 in lung conventional CD4+ T cells: these effects markedly reduced the eosinophilia and AHR." (PMID 37917548, 2023).
eosinophilia (continued). "When other eosinophilic asthma manifestations exist (nasal polyps, aspirin-exacerbated respiratory disease [AERD], atopic dermatitis or if eosinophilia persists after a short term of OCS), anti IL5/IL5Rα or dupilumab would be recommended." (PMID 36452259, 2022). "Interestingly, the marked increase in peritoneal IL-5+ Th2 cell numbers in the H. polygyrus-reinfected group was further paralleled by a significant influx of eosinophils into the peritoneal cavity, but not in other tissue sites, indicative of memory Th2-driven peritoneal eosinophilia." (PMID 35418979, 2022). "Current evidence supports the use of an anti-IL-5 mAb, mepolizumab (MEP), for the induction treatment of active or relapsing EGPA with eosinophilia." (PMID 34640595, 2021). "The P4rr was started on GD5, which is 6–7 days after the last OVA challenge to the mothers, a time after the OVA-induced 2–5 days peak in eosinophilia and when IL4 and IL5 have resolved in OVA-challenged adult mice." (PMID 34368802, 2021). "In addition, IL-13, which may induce eosinophilia in the lung depends largely on IL-5." (PMID 34625911, 2021). "As in wild type mice, CDG nearly abolished Alt-induced lung eosinophilia and reduced BAL IL-5 (p = 0.0518) in Rag2-/- mice." (PMID 33679760, 2021). "This Fab had moderate effects on BAL eosinophilia, but markedly reduced BAL IL-5 levels, which is in full agreement with our data obtained in HDM-exposed mice vaccinated with the IL-13-K." (PMID 33976140, 2021). "GMP administration significantly decreased IL-5, IL-13 and GATA3 expression in the intestinal tissue of FA animals, which is in accordance with reduced eosinophilia, goblet cell hyperplasia and IgE gene expression in small intestine of GMP treated rats." (PMID 32992996, 2020). "In our study, in a small population of patients with eosinophilia despite OCS treatment, we found normalization of BEC under anti-IL5 therapy." (PMID 32787967, 2020). "The immune response of sheep against GIN infections is primarily associated with the adaptive Th2-polarized profile, with local release of the interleukins IL4, IL5, and IL13, in addition to IgE production, eosinophilia, and mastocytosis." (PMID 31815153, 2019). "These alarmins are known to be natural triggers and enhancers of the Th2 type immune response, resulting in local and systemic induction of IL4, IL5, and IL13 synthesis, eosinophilia, and high levels of IgE." (PMID 31815153, 2019). "However, eosinophilia has been correlated with poor outcomes in mouse and human cryptococcosis, and in the presence of IM in our model, we observed an upregulation of pulmonary IL-5 and RANTES/CCL5, cytokines that play important roles in eosinophil maturation and trafficking." (PMID 30897162, 2019). "The production of IL-5, IL-4, and IFN-γ cytokines in peripheral blood were evaluated on the 18th day after infection, during the peak of eosinophilia." (PMID 29445372, 2018). "Two prominent cytokines, IL5 and IL13, which promote allergies and eosinophilia, are under the control of IRE1a-XBP1 pathway in Th2 lymphocytes." (PMID 30355343, 2018). "There was a positive correlations between sputum HMGB1 expressions in sputum eosinophilia and sputum TNF-a, IL-5 and IL-13 levels." (PMID 28630596, 2017). "Thus, IL-5 may increase the eosinophilia in both blood and sputum." (PMID 28761563, 2017). "Introduction of interleukin-5 (IL-5) was necessary to recapitulate typical features of HES/CEL, including hyper eosinophilia and tissue infiltration of eosinophils when co-expressed with F/P fusion gene." (PMID 29029406, 2017). "Recombinant HpARI co-administration with Alternaria allergen abrogated BAL eosinophilia and lung ILC2 IL-5 and IL-13 production, 24 hr later, again replicating the effects observed with total HES." (PMID 29045903, 2017). "They identified that IL-33 with IL-5, produced by ILC2, mediates the effect by induction of eosinophilia." (PMID 29163523, 2017).
eosinophilia (continued). "Intratracheal administration of LY294002 reduced OVA-induced increases in total cell counts, eosinophil counts, and IL-5, IL-13, and CCL11 (eotaxin) levels in BAL fluid and dramatically inhibited OVA-induced tissue eosinophilia and airway mucus production." (PMID 23690670, 2013). "However, several of the RA subjects had increased IL-5 in their sputum in the absence of substantial eosinophilia, suggesting that perhaps this residual IL-5 may be associated with the residual AHR." (PMID 23043798, 2012). "Transgenic overexpression in mice resulted in airway eosinophilia and elevated serum levels of the typical TH2-type cytokines IL-4, IL-5, and IL-13 together with increased IgE serum titers." (PMID 20976014, 2010). "It has been proved that Toxocara canis invasion promotes release of IL-5, IL-8, and TNF-α, which is accompanied by eosinophilia with an inflammatory state." (PMID 19478959, 2009). "Neonatal RSV infection followed by adult exposure to allergen resulted in significantly higher lung resistance, along with increased total cellularity, eosinophilia, and increased TNF-α and Th2 cytokines (IL-5 and IL-13) in BALF." (PMID 16893457, 2006). "In subcutaneously infected jirds, this eosinophilia peaks at approximately 28 DAI, and IL-5 mRNA levels increase between 14 and 28 DAI, indicating a role for the systemic IL-5 response in infected animals." (PMID 16542426, 2006). "Cytokines, including IL-5, IFN-gamma, GM-CSF also participate in delaying of the death process in these cells, thus contributing to developing of tissue and blood eosinophilia." (PMID 16551346, 2006). "Compared to sham-treatment, ISS-ODN-stimulated OVA-Mφ suppressed the airway eosinophilia by 85% (vs. 30% by unstimulated OVA-Mφ), IL-5 levels in bronchoalveolar lavage fluid by 80% (vs. 50%) and serum OVA-specific IgE levels by 60% (vs. 30%)." (PMID 15538945, 2004). "This latter study additionally showed that hyper-eosinophilia in 4-week-old IL-5 transgenic (CD3d-Il5; JAX#036943) mdx mice did not contribute significantly to muscle pathology." (PMID 39900735, 2025). "Surprisingly, concentrations of canonical Type 2 cytokines IL-4, IL-5, and IL-13 were highest in the primary infection mice, despite the lack of eosinophilia." (PMID 41190814, 2025). "As published data indicates that eosinophilia is not completely abolished in IL-5 ko mice, further investigation on how eosinophil development is promoted by type 2 immunity is needed." (PMID 40276331, 2025). "Surprisingly, despite the observed increased eosinophilia in IL-18R−/− mice, we did not observe any difference in IL-5+ Lin-Thy1.2+ ILCs between groups of mice at any time point." (PMID 40777291, 2025). "Overall eosinophilia during ICI therapy may predict subsequent irAEs, and tumor–eosinophil cross-talk (enhanced by IL-5/IL-33) is increasingly recognized as integral to both therapeutic responses and collateral immune adverse events." (PMID 40723182, 2025). "The absence of eosinophilia in this case, despite high IL-5 expression, suggests an activated Th2 component without peripheral hematological translation, a phenomenon described in some phases of certain viral inflammatory responses." (PMID 41441313, 2025). "In L-HES, eosinophilia is considered a reactive phenomenon secondary to the overproduction of eosinophilopoietic cytokines such as interleukin-5 (IL-5) and/or IL-3 by clonal T-cells, rather than a primary myeloid process." (PMID 41488087, 2025). "Furthermore, assessment of the ratio of eosinophilia in BAL cells and levels of Th2-type cytokines, including IL-5 and IL-13 in BAL fluid, showed a more marked increase in SLPI KO mice than in WT mice." (PMID 40546642, 2025). "Combinations of the type-2interleukins (IL)-4, IL-5, IL-9 and IL-13 promote immune effector functions includingantibody isotype switching to IgE, adaptive T helper 2 (TH2) cellpolarization, eosinophilia, mast cell hyperplasia, goblet cell hyperplasia and tissuerepair." (PMID 38935708, 2024).
eosinophilia (continued). "Finally, in OVA-sensitized BALB/c mice, TLR2/6 intratracheal administration before OVA challenge significantly decreased BAL IL-5 and IL-13 but increased BAL eosinophilia." (PMID 39273551, 2024). "Anti-IL-5 and anti-IL-5R biologics may show efficacy in AERD patients for disease and symptom control due to reduction in tissue eosinophilia, which has been beneficial for respiratory symptoms in AERD." (PMID 38673059, 2024). "This group includes patients with classified conditions associated with secondary eosinophilia, including EGPA (however, eosinophilia in EGPA is not entirely secondary, as it has a partially genetic background related to the IRF1/IL5 gene variant)." (PMID 37215720, 2023). "Although it correlates with airway eosinophilia in steroid-naïve patients, it can be independent from eosinophils and therefore not helpful in monitoring the response to anti-IL-5 mAb." (PMID 37108417, 2023). "Levels of IL-5 increase gradually in BAL fluid, which peaks 24 h after the challenge, suggesting that IL-5 may maintain lung eosinophilia whereas chemokines may exert biological activity for a shorter time (4-fold lesser length of time)." (PMID 37259416, 2023). "On the contrary, IL-5 induces eosinophilia but is unrelated to iNOS activation and does not contribute to NO levels." (PMID 37947596, 2023). "In contrast, in those treated with IL-5 inhibitors (mepolizumab), the levels of FeNO are not modified, but a significant effect on eosinophilia is appreciated." (PMID 37947596, 2023). "At the same time, IL-5 induces eosinophilia but is unrelated to iNOS activation and does not contribute to NO levels." (PMID 37947596, 2023). "Human eosinophils were reported to express IL-2 receptors; however, in vitro assays suggested that eosinophilia was due to IL-5, rather than direct effects of IL-2." (PMID 35699942, 2022). "In an early onset allergic USA patient, independently of blood eosinophil count, omalizumab will be the first choice while in a late onset non-allergic USA patient with eosinophilia, an anti-IL5/IL5Rα, or dupilumab will be considered." (PMID 36452259, 2022). "Given the major role of IL-5 in the recruitment of eosinophils, this likely explained why FTY720 treatment was ineffective in substantially reducing eosinophilia even though the accumulation of the majority of memory phenotype CD4 T cells was impaired upon HDM exposure." (PMID 35936001, 2022). "In another prospective study evaluating serum biomarker levels in EoE after PPIs therapy, a statistically significant negative correlation was found between IL-5 and esophageal eosinophilia and no prediction of the post-treatment tissue eosinophilia." (PMID 34203871, 2021). "High levels of IL-5 produced by Th2 responses to parasitic infections induces eosinophilia but has no adverse effects." (PMID 34912327, 2021). "The absence of BALF eosinophilia in mye-IL4Rα−/− mice and associated reduction in BALF levels of IL-4, IL-5, and eotaxin suggest that IL4Rα expression in myeloid cells is essential for eosinophil recruitment." (PMID 34326406, 2021). "In addition, the LRRC31 mRNA was positively correlated with eosinophilia and IL13 and IL5 expression, and was related to cellular immune regulation as well as inflammatory response." (PMID 34616724, 2021). "PD-L2 blockade at the time of allergen challenge, but not at sensitization, increased AHR and eosinophilia, in addition to IL-5 and IL-13 production, but reduced IFN-γ production in the lungs and lymph nodes." (PMID 33968057, 2021). "The failure of anti-IL-5 therapies, which while successful in reducing eosinophilia had no impact on COPD exacerbation rate in most individual studies, further weakens the concept of eosinophilia as an important contributor to the morbidity of COPD." (PMID 34739571, 2021). "This also explains the absence of reactive eosinophilia in both IL-5-KO-mice and long-term treatment with mepolizumab." (PMID 34409272, 2021).
eosinophilia (continued). "The role of IL-5 in acute experimental schistosomiasis shows that it is required for blood and tissue eosinophilia but not for granuloma formation." (PMID 34239575, 2021). "IFNγ monoclonal antibody blockade led to a modest non-significant increase in airway eosinophilia and IL-5+ ILC2s in mice challenged with Alt and CDG." (PMID 33679760, 2021). "A negative correlation with tissue eosinophilia can also be observed in the case of IL-13, the concentration of which, similarly to IL-5, significantly increases in the serum after treatment." (PMID 34203871, 2021). "In contrast, IL-33-induced bone marrow and airway eosinophilia were abolished in the absence of ILC2s in Rag2−/−Il2rg−/− mice and no production of IL-5 was detected in IL-33-stimulated bone marrow cultures." (PMID 32582171, 2020). "However, RAGE antagonism significantly decreased IL-5 levels in BALF, diminished airway eosinophilia, and critically, prevented aberrant ASM growth in infancy." (PMID 32658914, 2020). "Second, we did not evaluate other molecules that contribute to eosinophilia, such as IL‐2, IL‐3, IL‐5, GM‐CSF, and NKG2D." (PMID 31950647, 2020). "Utilising GLA, a suppression of eosinophilia, sneezing and IL-5 secretion were observed although the mechanism was not explored." (PMID 33281825, 2020). "Our data indicate that both CCR3-dependent ligands and IL-5 are necessary to induce eosinophilia to filarial infection in the absence of IL-4R signaling." (PMID 32571840, 2020). "Exposure to DEPs also resulted in increased levels of markers for both allergic (eosinophilia and IL-5 production) and nonallergic (macrophage chemoattractant protein-1, IL-8, and neutrophilia) inflammation in atopic human volunteers." (PMID 31983527, 2020). "Subsequently, it was established that IL-5, another important cytokine for tissue eosinophilia, is not necessary for eosinophil recruitment to the uterus." (PMID 31859912, 2020). "In line with results of these studies, our study clearly shows that treatment with recombinant Grx1 did not improve any of the analyzed parameters (such as eosinophilia, IL-5 release, or lung function)." (PMID 33224135, 2020). "In non-myeloid hematologic and solid neoplasms, eosinophilia results from the production of cytokines by malignant cells, mainly interleukin (IL)-5, such as in T cell and Hodgkin lymphoma, acute lymphoblastic leukemia." (PMID 31367340, 2019). "In this study, we provide evidence demonstrating that combined delivery of IL-2 immunocomplexes and anti-IL-5 mAb is highly effective at expanding Foxp3+ Treg cells in the absence of eosinophilia and ameliorating DSS-induced colitis in mice." (PMID 30930900, 2019). "Instead, the raised eosinophilia we observed in the absence of CD200R1 likely arises from the enhanced levels of eosinophilic chemoattractant cytokines IL‐5 and eotaxin‐2." (PMID 31365119, 2019). "Even more interesting was the fact that eosinophil progenitor cells did not vanish after anti-IL-5 treatment in these patients, which means that in situ eosinophilopoiesis is an important mechanism of persistent eosinophilia in the airways." (PMID 31480806, 2019). "The same applies to their mobilization from circulation to tissues, since administration of eotaxin-1 without abolishing IL-5 effects increases blood eosinophilia but fails to increase their number in tissue." (PMID 31480806, 2019). "In the refractory eosinophilic asthma without atopic background (high blood eosinophilia, high FeNO, normal IgE), an anti-IL5 antibody seems to be the most appropriate." (PMID 30598830, 2018). "In a subsequent study, elevated sputum IL-5 and submucosal airway eosinophilia (and not sputum) were documented to be significantly elevated in severe asthmatics with obesity." (PMID 29486749, 2018).